CMTM7 (CKLF like MARVEL transmembrane domain containing 7)
Diseases named in the same sentence as CMTM7 in open-access papers (continued):
Sharing a sentence is not in itself a finding about the gene and the disease.
tumor (19 papers, 2014 to 2024). "CMTM7 functions as a tumor suppressor in various types of cancer within the field of cancer research." (PMID 38933262, 2024). "CMTM7 has been determined to be downregulated in various cancers, and its overexpression inhibits cell proliferation and tumor formation." (PMID 39494610, 2024). "Promoter methylation is the mechanism by which CMTM7 expression is downregulated, and CMTM7 expression can affect cell proliferation and tumor development (Jin, Qin & Jia, 2018)." (PMID 38223763, 2024). "Mechanistically, miR-182-5p reduces expression of CKLF like MARVEL transmembrane domain containing 7 (CMTM7) tumour suppressor, leading to activation of EGFR/AKT signalling and subsequent angiogenic signalling, which was confirmed in vivo." (PMID 37670020, 2023). "In our study, we discovered that CMTM7 is a tumor suppressor that is regulated by methylation of its CpG island." (PMID 36829181, 2023). "Chemokine-like factor like MARVEL transmembrane domain containing 7 (CMTM7) is reported as a tumor suppressor and is involved in epidermal growth factor receptor degradation and PI3K/AKT signaling in previous studies." (PMID 36829181, 2023). "Among them, CMTM3 and CMTM7 have functional characteristics of tumor suppressors, which are co-located with early endosomal marker Rab5, regulating the traffic and stability of membrane molecules, such as EGFR, VE-cadherin and BCR." (PMID 35983975, 2022). "For example, it has been proven that CMTM3, CMTM4, CMTM5 and CMTM7 are new potential tumor suppressors, and interestingly, patients with high CMTM6 expression have a worse survival prognosis than those with low CMTM6 expression according to this study." (PMID 35983975, 2022). "As a tumor suppressor and newly identified regulator of Rab5 activation, CMTM7 also plays a role in regulating the autophagy process." (PMID 34281589, 2021). "This was further verified by xenograft tumor model in nude mice, which showed that knockdown of CMTM7 impaired autophagy and accelerated tumorigenicity in vivo." (PMID 34281589, 2021). "The results revealed that rapamycin reversed the promoting effects of tumor cell proliferation mediated by CMTM7 knockdown." (PMID 34281589, 2021). "Both in vitro and in vivo experiments demonstrated that CMTM7 knockdown promotes tumor growth via impairing cell autophagy." (PMID 34281589, 2021). "Taken together, these results suggested that CMTM7 knockdown-mediated autophagy suppression contributed to tumor cell proliferation." (PMID 34281589, 2021). "The tumor volume and weight of mice treated with EVs + miR-182-5p inhibitor were reduced while they were increased in the presence of further CMTM7 silencing." (PMID 34294040, 2021). "For example, LIN28B regulates let-7 miRNA, CMTM7 is potential tumor suppressor, possibly silenced by promoter methylation), and ARGHDIB, a regulator of Rho family signaling, can be upregulated in tumors." (PMID 33266012, 2020). "CMTM7 knockdown promotes tumor growth, whereas SOX10-dependent CMTM7 overexpression decreases the cancer cell proliferation rate, thus slowing tumor growth." (PMID 32944388, 2020). "CMTM7 is located on the chromosome 3p22 which is rich in tumor-suppressor genes and the promoter contains a typical CpG island." (PMID 33282744, 2020). "Liu 43 reported that CMTM7 was mainly expressed in the nuclei of tumor tissues of 127 lung adenocarcinoma patients, but in the cytoplasm and cell membrane of adjacent normal tissues." (PMID 31754330, 2019). "Together, our findings highlight the role of CMTM7 in the regulation of EGFR signaling in tumor cells, revealing CMTM7 as a novel molecule related to Rab5 activation." (PMID 26528697, 2015). "Our results indicate that the loss of CMTM7 in NSCLC cells positively regulates EGFR signaling by decreasing Rab5 activation, thereby promoting tumor growth and migration." (PMID 26528697, 2015).
tumor (continued). "This may be possibly due to decreased expression of cyclin D1, cyclin-dependent kinase 4 (CDK4) and CDK6 and increased expression of p27, indicating that CMTM7 acts as a tumor suppressor by inhibiting cell cycle progression in HCC." (PMID 38223763, 2024). "Additionally, high expression of CMTM7 is positively correlated with immunomodulators, tumor-infiltrating immune cells (TIICs), and immune checkpoint activation." (PMID 38223763, 2024). "The expression of CKLF, CMTM1, CMTM3, and CMTM7 was correlated with cancer stage and tumor grade." (PMID 36975415, 2023). "Similarly, CMTM7 had higher expression in normal breast tissues than in tumor tissues and related to earlier stages." (PMID 36829181, 2023). "As CMTM7 is a potential tumor suppressor and frequently deleted in many carcinomas, its dysfunction could promote oncogenesis and progression in multiple carcinomas." (PMID 36568362, 2022). "CKLF-like MARVEL transmembrane domain-containing 7 (CMTM7) is a potential tumor suppressor and regulator of PD-L1, which has been found as a functional signature in considerable oncogenesis, progression, and therapeutic resistance via deletion and downregulation." (PMID 36568362, 2022). "Moreover, CMTM7 positively correlated with immunomodulators, tumor-infiltrating immune cells (TIICs), and immune checkpoints in many independent datasets." (PMID 36568362, 2022). "CMTM7 can be a biomarker reflecting the progression and immune status of tumor samples." (PMID 36568362, 2022). "Therefore, through different regulator mechanisms on two classes of PI3K, CMTM7 more effectively exerts tumor-suppressive function." (PMID 34281589, 2021). "Another study indicated that the silence of CMTM7 could decrease Rab5 activation, promoting tumor growth and migration in non-small cell lung cancer." (PMID 33282744, 2020). "Given that CMTM7 is overexpressed in tumor tissues, it could be a candidate target in BRCA." (PMID 36568362, 2022). "Thus, CMTM7 might be considered to play a crucial role as a tumor suppressor by inversely regulating the two types of PI3K." (PMID 34281589, 2021). "CMTM7 is a tumor suppressor that positively regulates EGFR degradation by promoting Rab5 activation, and plays a vital role in tumor progression." (PMID 34281589, 2021). "They found CMTM7 was significantly downregulated in HCC tissues and cell lines (Hep3B, SK-HEP-1, Huh7, and HepG2), and exhibited tumor-suppressor activities." (PMID 33282744, 2020). "Limited clinical evidence of the direct tumor suppressor functions of CMTM5, CMTM7 and CMTM8 has been presented to date." (PMID 32944388, 2020). "As tumor grade increased, the mRNA expression of CKLF, CMTM1, CMTM3, and CMTM7 tended to be higher." (PMID 36975415, 2023). "In addition, in BRCA, the downregulation of CMTM7 can activate the EGFR/Akt signaling pathway to promote tumorigenesis and metastasis of tumor cells." (PMID 36568362, 2022). "There was no significant change in the expression of miR-182-5p in tumor tissues of mice treated with EVs + miR-182-5p inhibitor + si-CMTM7, while the expression of CMTM7 was reduced, and the EGFR and AKT phosphorylation levels were significantly increased." (PMID 34294040, 2021). "The expression of CMTM7 could be dynamically adjusted by transcription factor FLI1 and SOX10 during tumor pathogenesis." (PMID 33282744, 2020). "CMTM7 is a 3p22.3 tumor suppressor that is down-regulated or absent in esophageal tumor tissues with promoter methylation and loss of heterozygosity." (PMID 26528697, 2015). "CMTM5 and CMTM7 are both members of the CMTM family, and studies have shown that both in vitro and in vivo experiments demonstrated that knockdown of CMTM7 enhanced tumor growth by impairing autophagy, indicating that CMTM5 may participate in tumor development by mediating autophagy." (PMID 39166861, 2024).
cancer (17 papers, 2012 to 2024). A tumor composed of atypical neoplastic, often pleomorphic cells that invade other tissues. "Univariate Cox analysis revealed that the expression of CMTM1, CMTM4, CMTM7, and cancer stage were significantly associated with poor prognosis in patients with HCC (p < 0.05)." (PMID 36975415, 2023). "We identify SLFN11, ETV4, HNRNPA1, and CMTM7 as promising markers of drug sensitivity in a number of common cancers." (PMID 39494610, 2024). "The mRNA expression of CKLF, CMTM1, CMTM3, CMTM4, and CMTM7 was correlated with the cancer stage, revealing that patients with more advanced cancer stages tended to have higher mRNA expression of the CMTM family." (PMID 36975415, 2023). "The mass spectrometry results of CMTM7 had addressed plenty of genes that could interact with CMTM7, which was followed by enrichment analysis and focused primarily on Wnt signaling when screened with cancer-related pathways." (PMID 36829181, 2023). "Overexpression of CMTM7 could inhibit cancer cells (KYSE410 and KYSE180) growth by inducing G1/S phase arrest and repressing EGFR-PI3K/AKT signaling in KYSE180 cells." (PMID 33282744, 2020). "In addition, CMTM7 also inhibits cancer cell growth and represses oncogenic EGFR signaling by promoting EGFR internalization and further suppressing the Akt signaling pathway." (PMID 32328181, 2020). "TargetScan website predicted the binding sites between miR-182-5p and CKLF-like MARVEL transmembrane domain-containing 7 (CMTM7), a member of the CMTM family playing key roles in the occurrence and progression of cancer." (PMID 34294040, 2021). "For instance, CMTM7, another member of the CMTM family, has been shown to inhibit cancer cell growth by inhibiting oncogenic EGFR signalling and the Akt signalling pathway." (PMID 29213215, 2017). "It has been reported that some CMTM family members, such as CMTM7 and CMTM8 exert their roles in human cancers by influencing RTK and RTK-related signaling pathways." (PMID 27121055, 2016). "Only CMTM7 expression is frequently suppressed or reduced in esophageal and nasopharyngeal cell lines, but this is not true for other cancer cell lines." (PMID 38223763, 2024). "Previous studies have found that CMTM7 is frequently downregulated or absent in some cancers, partly because of the aberrant promoter CpG methylation and loss of heterozygosity." (PMID 33282744, 2020). "Finally, the Bayesian model also revealed other recurrent genes, FAM60A (family with sequence similarity 60, member A), CMTM7 (CKLF-like MARVEL transmembrane domain 7) and DDX55 (DEAD (Asp-Glu-Ala-Asp) box polypeptide), currently not reported to be involved in cancer progression." (PMID 22280244, 2012).
CMTM7 also shares sentences with these, for which no sentence is quoted: non-small cell lung carcinoma (2 papers); atherosclerosis (1); B-cell lymphoma (1); colorectal cancer (1); hypopharyngeal cancer (1); lip (1); lung adenocarcinoma (1); pancreatic cancer (1); periodontitis (1).